DUSP13B (dual specificity phosphatase 13B)
Description:
Dual specificity phosphatase that dephosphorylates MAPK8/JNK and MAPK14/p38, but not MAPK1/ERK2, in vitro. Exhibits intrinsic phosphatase activity towards both phospho-seryl/threonyl and -tyrosyl residues, with similar specific activities in vitro.
Synonyms: DUSP13; SKRP4; TMDP; MDSP
Tractability: No criterion of Open Targets' tractability assessment is met for any kind of drug.
Gene: Protein-coding gene on chromosome 10 (75,094,432 to 75,106,499, reverse strand). Ensembl gene ENSG00000079393.
Gene Ontology:
Molecular function: phosphatase activity; protein binding; MAP kinase phosphatase activity; protein serine/threonine phosphatase activity; protein tyrosine phosphatase activity; protein tyrosine/serine/threonine phosphatase activity
Biological process: dephosphorylation; meiotic cell cycle; negative regulation of MAPK cascade; protein dephosphorylation; spermatogenesis
Cellular component: cytoplasm
Genetic constraint (gnomAD): Loss-of-function variants: 33 observed, 31.36 expected, observed/expected ratio (o/e) 1.05, 90% interval 0.8 to 1.41. The upper end of that interval is the gene's LOEUF score, 1.41, which puts it in group 5 of 6, group 1 being the genes least tolerant of losing a copy. Missense variants: 383 observed, 419.02 expected, observed/expected ratio (o/e) 0.91, 90% interval 0.84 to 1. Synonymous variants: 140 observed, 164.54 expected, observed/expected ratio (o/e) 0.85, 90% interval 0.74 to 0.98.
Homologues: Orthologues: chimpanzee DUSP13B (98% identical), dog DUSP13B (75% identical), mouse Dusp13b (70% identical), macaque DUSP13B (63% identical), rat Dusp13b (58% identical), guinea pig DUSP13B (54% identical), zebrafish dusp13a (30% identical), zebrafish si:dkey-24f15.2 (17% identical). Paralogues in human: DUSP29 (28% identical), DUSP26 (26% identical), DUSP13A (25% identical), DUSP3 (22% identical), STYXL2 (20% identical), DUSP14 (18% identical), SSH3 (18% identical), SSH2 (17% identical), DUSP4 (16% identical), DUSP1 (16% identical), DUSP2 (16% identical), DUSP21 (16% identical), and 19 more.
Diseases named in the same sentence as DUSP13B in open-access papers:
DUSP13B is named in the same sentence as 4 diseases in open-access papers, as found by Europe PMC text mining. Sharing a sentence is not in itself a finding about the gene and the disease. The quoted sentences say what the papers report.
lung adenocarcinoma (1 paper, 2025). A carcinoma that arises from the lung and is characterized by the presence of malignant glandular epithelial cells. "Conversely, the mRNA level of DUSP13B was downregulated in lung adenocarcinoma tissues with EGFR mutations (P = 0.025)." (PMID 39721017, 2025). "We also analyzed the association between SHH, DUSP13B, and p‐STAT3 proteins in lung adenocarcinoma tissues and found that p‐STAT3 was significantly positively correlated with SHH but negatively correlated with DUSP13B." (PMID 39721017, 2025). "In addition, we conducted IHC staining on 108 lung adenocarcinoma tissues and assessed the association between the protein levels of SHH, DUSP13B, p‐STAT3, and EGFR gene mutation status." (PMID 39721017, 2025). "The association among expression of SHH, DUSP13B, and p‐STAT3 proteins in lung adenocarcinoma." (PMID 39721017, 2025). "In lung adenocarcinoma, p‐STAT3 is positively correlated with SHH but negatively correlated with DUSP13B." (PMID 39721017, 2025). "We then utilized the GEPIA2 online platform to examine the correlation among the mRNA levels of SHH, GLI1, DUSP13B, and STAT3 in lung adenocarcinoma tissues from the TCGA dataset." (PMID 39721017, 2025).
lung carcinoma (1 paper, 2025). "To accurately determine the expression level of the SHH/DUSP13B/p‐STAT3 axis in osimertinib‐resistant lung cancer tissues, we collected 10 pairs of clinical lung cancer tissue specimens before and after osimertinib resistance and conducted IHC staining." (PMID 39721017, 2025). "Furthermore, DUSP13B protein was mainly expressed in the cytoplasm, with lower expression levels observed in postosimertinib‐resistant lung cancer tissues." (PMID 39721017, 2025). "Moreover, our study highlights the clinical relevance of these findings, demonstrating the increased expression of SHH, p‐STAT3, and GLI1 proteins in postosimertinib‐resistant lung cancer tissues, along with decreased DUSP13B expression." (PMID 39721017, 2025).
cancer (1 paper, 2025). A tumor composed of atypical neoplastic, often pleomorphic cells that invade other tissues. "This further suggests that DUSP13B may have a negative regulatory relationship with p‐STAT3, and further verification of this finding is needed in other types of cancer tissues in future studies." (PMID 39721017, 2025).
DUSP13B also shares sentences with these, for which no sentence is quoted: tumor (1 paper).